ZNF428 (zinc finger protein 428)
Synonyms: C19orf37; MGC51082; Zfp428
Tractability: No criterion of Open Targets' tractability assessment is met for any kind of drug.
Gene: Protein-coding gene on chromosome 19 (43,607,223 to 43,619,639, reverse strand). Ensembl gene ENSG00000131116.
Subcellular location (Human Protein Atlas): Mitochondria; Nucleoli
Gene Ontology:
Molecular function: protein binding
Genetic constraint (gnomAD): Loss-of-function variants: 5 observed, 15.51 expected, observed/expected ratio (o/e) 0.32, 90% interval 0.17 to 0.68. The upper end of that interval is the gene's LOEUF score, 0.68, which puts it in group 2 of 6, group 1 being the genes least tolerant of losing a copy. Missense variants: 237 observed, 253.63 expected, observed/expected ratio (o/e) 0.93, 90% interval 0.84 to 1.04. Synonymous variants: 97 observed, 102.49 expected, observed/expected ratio (o/e) 0.95, 90% interval 0.8 to 1.12.
Homologues: Orthologues: macaque ZNF428 (100% identical), chimpanzee ZNF428 (98% identical), dog ZNF428 (98% identical), pig ZNF428 (96% identical), rabbit ZNF428 (96% identical), guinea pig ZNF428 (96% identical), rat Zfp428 (91% identical), mouse Zfp428 (91% identical).
Diseases named in the same sentence as ZNF428 in open-access papers:
ZNF428 is named in the same sentence as 3 diseases in open-access papers, as found by Europe PMC text mining. Sharing a sentence is not in itself a finding about the gene and the disease. The quoted sentences say what the papers report.
ovarian tumor (1 paper, 2020). "In the library prepared from ovarian tumor tissue, 5 clones with coding sequences were identified using the HMGB1 bait (C1QA, DAG1, RPL29, RSF1, TGM2), and 6 (COMMD1, MIEN1, PCBP1, TBC1D25, ZFR, ZNF428) were identified with the HMGB2 bait." (PMID 32867128, 2020).
ovary cancer (1 paper, 2020). "HMGB1 and HMGB2 genes were silenced in SKOV-3 and PEO1 EOC cell lines and levels of mRNA from 4 detected interacting partners of HMGB1 or HMGB2 in ovary cancer, COMMD1, MIEN1, NOP53 and ZNF428, were analyzed by qRT-PCR as explained in Materials and Methods." (PMID 32867128, 2020).
ZNF428 also shares sentences with these, for which no sentence is quoted: cancer (1 paper).